KRAS (KRas proto-oncogene, GTPase)
Diseases named in the same sentence as KRAS in open-access papers (continued):
Sharing a sentence is not in itself a finding about the gene and the disease.
lung cancer (continued). "Furthermore, the efficacy of a second covalent inhibitor of KRAS G12C, adagrasib, was presented at the European Lung Cancer Virtual Conference in early 2021, where the multi-cohort phase I/II trial showed a 45% ORR in 51 advanced, typically pre-treated NSCLC patients." (PMID 34198738, 2021). "Therefore, changes in KRAS expression might not be detectable, neither in blood nor in tumor tissue, except with observed by us the age-relative of KRAS gene expression in lung cancer tissue." (PMID 33549031, 2021). "Simultaneous genomic changes may impact biological behaviors, such as treatment response; thus, the investigation of co-occurring genomic alterations could help to stratify KRAS-mutant lung cancer patients into distinct subgroups with distinctive therapeutic responses." (PMID 34684076, 2021). "Furthermore, some data support the hypothesis that there could be an interplay between KRAS epigenetic regulation and lung cancer pathogenesis, suggesting a sophisticated balance between genomic and epigenomic features and lung cancer development." (PMID 35004317, 2021). "However, it remains unknown whether SDPR could be a predictor or target for lung cancer, especially in KRAS-mutant group." (PMID 33435990, 2021). "Moreover, ACSL3 has been shown to be essential for mutant KRAS lung cancer tumorigenesis." (PMID 34790661, 2021). "KRAS is not only able to impair the differentiation of endodermal progenitors in vitro when exposed to retinoic acid, but also promotes maintenance and expansion of TICs in breast cancer, keratinocytes, prostate cancer, colon cancer, pancreatic cancer and lung cancer." (PMID 32823550, 2020). "Until now, a lack of effective therapeutics persists for KRAS mutation-driven lung cancer." (PMID 32641008, 2020). "KRAS may be a good lung cancer therapeutic target for searching potential drugs." (PMID 32117436, 2020). "In addition, it was found that any history of smoking significantly increased the possibility of finding KRAS mutations in lung cancer, regardless of the number of years of smoking." (PMID 32342665, 2020). "However, whether the NLRP3 inflammasome is also activated in KRAS-induced solid tumours such as pancreatic and lung cancers remains elusive, and requires further investigation." (PMID 33116132, 2020). "Additionally, the potential of DGKη to regulate MAPK signaling, which is a downstream target of epidermal growth factor receptor (EGFR), led a group to study the oncogenic effects of DGKη in lung cancer, which is often characterized by mutations in EGFR and KRAS." (PMID 32722576, 2020). "Notably, loss of Usp18 in KrasLA2/+ mice has been reported to significantly attenuate lung cancer formation, compared to parental KrasLA2/+ mice harboring activated KRAS, pinpointing the implication of USP18 as a potential therapeutic target for cancer treatment." (PMID 32957626, 2020). "Hence, SNORD50A/B acts as a negative regulator of the KRas pathway irrespective of its mutational status, and affects tumorigenic capacities of cancer cells, including lung cancer cells." (PMID 32111002, 2020). "Thus, this study will provide a clinical benefit to KRAS-mutant lung cancer studies." (PMID 32728173, 2020). "But it is still not clear how the KRAS mutation triggers lung cancers." (PMID 32117436, 2020). "Finally, our data suggest that IKKβ kinase inhibition therapy may clinically benefit KRAS-driven lung cancer patients by depleting the pool of stem-like TICs, thereby decreasing the risk of tumour recurrence and metastasis." (PMID 32823550, 2020).
lung cancer (continued). "In conclusion, our results show that IKKβ promotes KRAS-induced stem-like and malignant traits, which indicates that IKKβ is likely involved in promoting tumour recurrence and aggressiveness, thereby suggesting IKKβ inhibition as a relevant therapeutic approach for KRAS-induced lung cancer." (PMID 32823550, 2020). "Additionally, mutations in the KRAS, BRAF, and PIK3CA genes have emerged as an important predictive marker of resistance to epidermal growth factor receptor (EGFR)-targeting monoclonal antibodies or tyrosine kinase inhibitors in colorectal and lung cancers." (PMID 33054840, 2020). "A differential effect of AGTPBP1 expression on the genetical subtypes of lung cancer could be investigated using additional lung cancer cell lines without KRAS mutation such as HCC78 and EBC-1 in future study." (PMID 33276627, 2020). "This may partly explain why driver mutations, including EGFR, ALK, and KRAS, were not identified in lung cancer patients." (PMID 31069172, 2019). "The discovery of selective KRAS G12C inhibitors presents great promise for the treatment of lung cancers that are driven by this mutation, but these inhibitors will not be effective for other cancers with lower prevalence of KRAS G12C mutations, such as colorectal (12%) and pancreatic (4%) cancers." (PMID 31878223, 2019). "In addition to KRAS and EGFR T790 mutations, the expression of oncogenes, including MET, HER2 (ERBB2), and epidermal growth factor receptor 3 (HER3, ERBB3), is associated with drug resistance against EGFR-TKIs and leads to tumor recurrence in lung cancers." (PMID 31619200, 2019). "Moreover, ADAM17 inhibition may serve as a new indirect avenue to target the oncogenic activities of mutant KRAS in cancers including lung cancer (i.e., LAC), CRC and pancreatic cancer." (PMID 31438559, 2019). "Importantly, KRA-533 significantly reduces tumor burden in the lungs of both LSL-KRASG12D and KL mice, leading to prolonged survival compared to the untreated control group, suggesting that KRA-533 has potential to improve the prognosis of mutant KRAS driven lung cancer." (PMID 30971271, 2019). "Moreover, miR-1205 could act as a tumor suppressor in nonsmall cell lung cancer by disconnecting the synergy between KRAS and MDM4/E2F116." (PMID 31801947, 2019). "Furthermore, KRAS G13 alterations were present in two lung cancer patients." (PMID 31546879, 2019). "Similarly, in lung cancer samples, KRAS G12 was the most concordant hotspot (4/12)." (PMID 31546879, 2019). "A previous meta-analysis demonstrated that the presence of KRAS mutations was a negative prognostic factor for the overall survival of patients with lung cancer, but a more recent study showed that only the presence of KRAS mutations in exon 2 had a predictive value in adenocarcinoma (ADC) patients." (PMID 30048458, 2018). "However, no further stratifications have been available for lung cancer patients and KRAS mutations." (PMID 29504894, 2018). "Therefore, we could not assess the potential preferential benefit of palbociclib in patients with KRAS mutant lung cancer." (PMID 30647837, 2018). "Moreover, the KRAS mutations have been shown in lung cancer to be a negative predictor of EGFR inhibitors." (PMID 30406144, 2018). "We sought to identify progression mediators of KRAS-driven lung cancer, thus we resourced TCGA datasets to determine whether amplification and copy number-driven expression of the 28 metastasis-enriched genes from the screen correlated with KRAS mutation status in lung adenocarcinoma patients." (PMID 30013058, 2018).
lung cancer (continued). "In addition, lung cancer in general has high rate of aerobic glycolysis (hence the clinical use of PET imaging), which becomes even more prominent in the setting of KRAS and LKB1 mutations, therefore making the use of phenformin even more relevant." (PMID 28938614, 2017). "Thus, we hypothesized that detecting the KRAS and EGFR mutation of cfDNA in liquid biopsies by CAST‐PCR may be applied to monitor the disease progression of lung cancer during therapy." (PMID 28382702, 2017). "In conclusion, KRAS and EGFR mutations can be detected in peripheral blood as an alternative and supplement to tissue analysis; and quantitative levels of cfDNA, pmKRAS, and pmEGFR are associated to the clinical outcome of the surgical treatment of lung cancer." (PMID 28382702, 2017). "To explore the molecular mechanisms of how RANKL/RANK might affect the growth of lung cancer cells, we first isolated primary pneumocytes from KRas;rank+/+ and KRas;rankfl/fl mice and infected them with AdCre to knock out RANK and at the same time induce oncogenic KRasG12D." (PMID 29118048, 2017). "Furthermore, a high or perfect concordance between primary tumour and metastasis has been seen in colorectal and lung cancer and between areas with different growth patterns within lung adenocarcinomas when looking at common driver mutations such as EGFR, KRAS, NRAS and BRAF." (PMID 28347348, 2017). "Therefore, our results suggested honokiol induced autophagy in KRAS mutant lung cancer cells could be attributed to Sirt3- Hif-1α pathway." (PMID 28443025, 2017). "Interestingly, we observed that low miR-23a and high miR-23b-3p/27b-3p expression profiles were characteristic of our EGFR-mutated cancers, but were not characteristics of the KRAS-mutated lung cancers." (PMID 28035073, 2017). "Moreover, that we found IL-6 mRNA-positive cancer cells in KRAS mutation-negative cases suggests the potential for IL-6-targeted therapy to be applied to various types of lung cancer." (PMID 28951614, 2017). "Researchers have found tumor mutational frequencies and spectra differences between smokers and nonsmokers, as indicated by the reported differences in the frequency of somatic mutations of EGFR and KRAS observed between smoking and nonsmoking lung cancer patients." (PMID 27227356, 2016). "KRAS mutation in lung cancer is about 26% in smoker patients and 6% in never smokers." (PMID 27433281, 2016). "The other most important alteration in lung cancer, KRAS mutation, does not occur in a TKR gene." (PMID 27528792, 2016). "Finally, Aurora kinase pharmacological inhibition preferentially targets lung cancer cells expressing KRASG12V, thereby supporting our hypothesis that AURKA and AURKB are promising targets for KRAS-induced lung cancer therapy." (PMID 26842935, 2016). "We have further described that WSE related lung cancer is associated with an older age at diagnosis, adenocarcinoma histology, pleural effusion, high prevalence of EGFR mutations (55.4 %) and a low prevalence of KRAS mutation (6 %), compared to patients with smoking history." (PMID 27098372, 2016). "KRAS mutation group was not included in this study because the incidence of KRAS is low (<10%) in the Chinese population, and the analysis of KRAS mutation is not routinely performed in patients with lung carcinomas." (PMID 27648828, 2016). "Therefore, developing non-cardiotoxic selective COX-2 inhibitors and/or agents that target the enzymes regulating PGE2 synthesis and degradation may lead to valuable chemopreventive or -therapeutic approaches for patients with mutant KRAS lung cancer." (PMID 26452035, 2015). "For KRAS-driven cancer, although much research has been focused on the KRAS4B splice variant, which does not undergo palmitoylation, KRAS4A has recently been shown to play an essential role in the development of carcinogen-induced lung cancer in mice and to be widely expressed in human cancers." (PMID 26715448, 2015).
lung cancer (continued). "Treatment of lung cancer has moved towards individualized treatment using the combined assessment of immunohistochemical markers, mutational analyses, and FISH techniques in order to assess the exact histology and to detect, for example, KRAS and EGFR mutations or ALK translocations." (PMID 25968475, 2015). "Because ER-α is highly targetable by a number of pharmaceutical compounds, to further explore whether ER-α may represent a new drug target for a subgroup of KRAS MT lung cancers, we performed IHC analysis on an independent study set of 90 archived NSCLC samples." (PMID 26468985, 2015). "Since there is a significant association between KRAS mutations and smoking behaviors, the relatively high rate of non-smoking lung cancers in Taiwan might be one reason for the lower KRAS mutation rate in the present study." (PMID 25789627, 2015). "In this study, we aimed to determine whether an inhibitory phenotype can account for the mutual exclusivity of KRAS and EGFR mutations in LUAD and to characterize the specific cellular effects that result from co-expression of both mutant alleles in lung cancer cells." (PMID 26047463, 2015). "Therefore, identification of druggable targets in the KRAS signaling pathway could lead to novel therapeutic alternatives for lung cancer, as well as other RAS-driven cancers." (PMID 24955217, 2014). "Furthermore, when KRAS or IKKβ expression was reduced by transfecting human lung cancer cell lines with siRNA targeting either KRAS or IKKβ, NF-κB luciferase reporter activity was also inhibited, indicating that, in these cells, both KRAS and IKKβ are promoting NF-κB activity." (PMID 24955217, 2014). "Interestingly, knockdown of IKKα in the lung cancer cells studied not only reduced NF-κB activity, but more importantly, inhibition of KRAS, IKKβ or IKKα by siRNA in H358 cells inhibited IκBα phosphorylation and degradation, a hallmark of the canonical NF-κB activation pathway." (PMID 24955217, 2014). "Additionally, most ALK-positive lung cancer is mutually exclusive to EGFR and KRAS mutations." (PMID 23936355, 2013). "KRAS mutations are frequently found in human malignancies and notably up to 60% in lung adenocarcinoma, being the second most frequently mutated gene in lung cancer." (PMID 24212941, 2011). "Despite decades of intensive analysis of the Ras family of proto-oncogenes (HRAS, NRAS, and KRAS) and corresponding biological processes 2,4], the downstream phosphorylation targets and pathways regulated by oncogenic Ras-mediated signaling remain to be elucidated in lung cancer." (PMID 21637843, 2011). "However, such small molecule therapy is not suitable for most lung cancer events, including cancer caused by a mutated KRAS gene." (PMID 21079797, 2010). "Our findings demonstrate that ZC3H15 promotes lung cancer progression through activation of the AKT-mTOR pathway in these cells, suggesting a potential functional interaction with oncogenic KRAS signaling." (PMID 41513632, 2026). "Here, we found that molecular therapy targeted toward EGFR mutant, KRAS mutant, or ALK fusion lung cancer induced cholesterol biosynthesis, which promoted cancer cells to enter dormancy and thus escape drug killing." (PMID 41983392, 2026). "Among lung cancer cases, <5% were EGFR positive, 15.1% were KRAS positive, and 22.3% of NSCLC cases had a PDL1 of >1%, of which 14.2% were >50%." (PMID 41294703, 2025). "A sustained activation of the pathway due to activating alterations of Kirsten rat sarcoma viral oncogene homolog (KRAS) (12–30%) and BRAF (4%) is frequently observed in lung cancer samples." (PMID 41008623, 2025). "Previous studies showed that oncogenic KRAS and activated epidermal growth factor receptor (EGFR) promoted FASN expression via ERK in pancreatic and lung cancer cells." (PMID 40621620, 2025).
lung cancer (continued). "KEAP1 mutations—which often co-occur with STK11 in smoking-related lung cancers—are also enriched in KRAS-mutant NSCLC, found in roughly 10–20% of KRAS G12C tumors, defining a distinct subset." (PMID 40723270, 2025). "In patients with KRAS and LKB1 co-mutant lung cancer, autophagy in cancer cells increases acetyl-coenzyme A (acetyl-CoA) levels, inducing EMT and promoting metastasis through the acetylation of the transcription factor Snail." (PMID 40557151, 2025). "KRAS, however, is by far the dominant homolog which may explain its prevalence in ∼15% of all human cancers, but does not explain its involvement in a high percentage of lung cancer mutations." (PMID 40970185, 2025). "For instance, in lung cancer, BCL6 is regulated by the MAPK/ELK1 axis and facilitates KRAS‐driven tumorigenesis." (PMID 41438489, 2025). "In recent years, with the continuous advancement of lung cancer treatment strategies, genes such as HER2, KRAS, and NTRK have emerged as significant targets for targeted therapy in NSCLC." (PMID 40496619, 2025). "The Kirsten rat sarcoma (KRAS) oncogene was considered “undruggable” until the development of sotorasib, a KRASG12C selective inhibitor that shows favorable effects against lung cancers." (PMID 39400496, 2025). "Specifically, in the field of lung cancer, this catalog advocates the inclusion of PD-L1, EGFR, ALK, ROS-1, KRAS, NTKR, RET, and MET." (PMID 40261489, 2025). "Therefore, we next examined whether KRAS mutants induce PTX resistance in lung cancer cells." (PMID 39960727, 2025). "Gene modification through the introduction of various genes is valuable for studying the pathogenesis, metastasis, and drug resistance mechanisms of lung cancer, as well as for evaluating the efficacy of targeted therapies like EGFR and KRAS inhibitors." (PMID 40387186, 2025). "The first clinical breakthrough was achieved with sotorasib (AMG 510), an irreversible covalent inhibitor targeting KRAS G12C, which received FDA approval for advanced non–small cell lung cancer (NSCLC)." (PMID 41514544, 2025). "Both positive regulation of growth and regulation of growth pathways capture oncogenic signaling (e.g., EGFR, KRAS, and Hippo/YAP) that drive proliferation, metabolic adaptation, and immune evasion in lung cancer." (PMID 41228248, 2025). "In lung cancer cells, inhibition of NSD2-mediated H3K36me2 results in growth retardation by suppressing KRAS-driven transcriptional program." (PMID 41301842, 2025). "In KRAS- and BRAF-driven lung cancer models, dietary supplementation with NAC and vitamin E reduced ROS levels and oxidative DNA damage in tumors." (PMID 40646353, 2025). "Taken together, these results indicate that RASON upregulates KRAS signaling and suppresses macrophage infiltration via upregulation of CD47, thereby promoting lung cancer progression and facilitating innate immune evasion." (PMID 40128846, 2025). "For instance, mutant KRAS upregulates long-chain-fatty-acid–CoA ligase (ACSL) expression, thereby increasing β-oxidation and ATP production to support lung cancer development." (PMID 38698462, 2024). "KRAS is an oncogene of the MAPK signaling pathway, accounting for approximately 15%-30% of lung cancers." (PMID 39802954, 2024). "Oncogenic KRAS potently induced COX2 in both mouse and human lung cancer, which was suppressed using KRAS inhibitors." (PMID 38635884, 2024). "Initially, lentiviral CRISPR-Cas9 technology was employed to knockout YY1 in multiple EGFR-mutant, KRAS-altered, or ALK-rearranged lung cancer cell lines using two independent sgRNAs, and cell viability was significantly inhibited without exception." (PMID 39604408, 2024). "We revealed that KRASG12C inhibitors enhance the formation of primary cilia and Hh signaling, and that inhibition of Hh signaling blocks re-expression of KRAS and reactivation of ERK in lung cancer cells treated with a KRASG12C inhibitor." (PMID 38225225, 2024).